PPARG (peroxisome proliferator activated receptor gamma)
Diseases named in the same sentence as PPARG in open-access papers (continued):
Sharing a sentence is not in itself a finding about the gene and the disease.
Hepatic steatosis (continued). "Therefore, in male PPARα−/− mice, the loss of Pparα expression leads to the compensatory upregulation of the Pparγ and the regulation of the expression of genes with PPRE, resulting in the development of fatty liver." (PMID 36140300, 2022). "Finally, among the DEGs, some are also key regulators of hepatic lipid metabolism (e.g., PIK3R1, PPARG, S100A11), suggesting that alterations in TIA1 expression/activity also contribute to fatty liver disease development." (PMID 35406476, 2022). "PPARγ agonist rosiglitazone has shown the impact of resolution on hepatic steatosis but not on NASH." (PMID 34745420, 2021). "PPARγ and CD36 mRNA expression are up-regulated in high-fat diet-induced liver steatosis in mice." (PMID 33513874, 2021). "For PPARγ, compared with the control group, there were no significant changes in the mild fatty liver, moderate fatty liver, and severe fatty liver groups (P > 0.05)." (PMID 33879188, 2021). "Interestingly, PGZ is more effective in treating fatty liver disease than RGZ, the more potent PPARγ agonist, suggesting that moderate binding is more effective." (PMID 34128467, 2021). "Our results show that Göttingen Minipigs do not develop abundant hepatic steatosis in spite of the significantly increased expression of PPARG, FABP4, CD36, and LPL in the liver." (PMID 32205840, 2020). "Next, we examined whether the HNF4α levels were significantly downregulated and/or the PPARγ levels were upregulated in the case of NASH, a more severe stage of fatty liver disease." (PMID 32235813, 2020). "We hypothesized that PPARγ-mediated fatty acid uptake and TAG synthesis might be involved in VPA-induced hepatic steatosis." (PMID 31379584, 2019). "Here, we report that Smurf1 induces non-proteolytic ubiquitination of PPARγ and inhibits PPARγ transcriptional activity in hepatocytes, thereby acting as a critical safeguard against the development of hepatic steatosis." (PMID 30566427, 2018). "Accordingly, the overexpression of PPARγ and SLC10A2 in the HFD group might be a vital reason for hepatic steatosis." (PMID 30096951, 2018). "PPARγ activation in liver contributes to hepatic steatosis and is not indispensable for insulin sensitization, depending on the diverse rodent backgrounds studied." (PMID 28611668, 2017). "In contrast to RSG, INT131 did not aggravate hepatic steatosis or affect hepatic adipogenic gene expression, although it did generate equivalent or more potent PPARγ activation and regulation of downstream target genes in adipose tissues and skeletal muscle." (PMID 28611668, 2017). "Hepatic PPARγ activation induces the up-regulation of downstream target genes involved in adipogenesis, and lipid metabolism is responsible for RSG-induced hepatomegaly and hepatic steatosis." (PMID 28611668, 2017). "To identify the molecular mechanism with regard to the inhibitory effect of KBH-1 on hepatic steatosis, we investigated the effect on the activation of AMPK, ACC and PPARγ proteins or the expression of SREBP-1c, ACC and 3-hydroxy-3-methylglutaryl CoA reductase (HMGCR) genes." (PMID 27618865, 2016). "The genetic deletion of Pparγ in livers of either ob/ob or AZIP-F-1 mice significantly alleviated the development of hepatic steatosis, which was independent of the existence of hyperglycemia or hyperinsulinemia." (PMID 27973423, 2016). "On the other hand, the nuclear transcription factor peroxisome proliferator-activated receptor γ (PPARγ), which is a pivotal regulator of lipid metabolism, may also play a critical role in VPA-induced fatty liver disease." (PMID 27034954, 2016). "As opposed to C57Bl/6 mice, HFD induced marked liver steatosis and upregulated the hepatic LXRα and PPARγ genes in BALB/c mice." (PMID 26218873, 2015). "Accordingly, targeted deletion of PPARγ in hepatocytes and macrophages protected mice against diet-induced hepatic steatosis, suggesting a pro-steatotic role of PPARγ both in parenchymal and non-parenchymal cells." (PMID 26035752, 2015).
Hepatic steatosis (continued). "Here, we found that RGZ treatment increased adiponectin, PPARα, PPARγ and AMPK activation, suggesting that these factors may be involved in the RGZ-mediated amelioration of hepatic steatosis." (PMID 21373642, 2011). "Adenovirally driven PPARγ gene when injected through tail vein induced hepatic steatosis in both PRIC285 null and wild type floxed littermates to delineate the role of the coactivator PRIC285 in hepatic steatosis." (PMID 20814439, 2010). "However, in multiple clinical trials, PPARγ agonists improve hepatic steatosis in patients with nonalcoholic steatohepatitis." (PMID 38039287, 2023). "Moreover, Curc-mPEG454 reversed HFD-induced hepatic steatosis and hypertriglyceridemia by modulating the hepatic CREB/PPARγ/cluster of differentiation 36 (CD36) pathway through the activation of CREB phosphorylation and inhibition of PPARγ and CD36 expression." (PMID 37762669, 2023). "Indeed, the PPARγ agonist pioglitazone and PPARα fenofibrate reduced atherosclerosis and hepatic steatosis in mice lacking both ApoE and Farnesoid x receptor (FXR), which modeled NASH and atherosclerosis simultaneously." (PMID 37200978, 2023). "Notably, oral M. funiformis CML154 significantly attenuated hepatic steatosis, reduced the accumulation of hepatic and serum lipids (TG and TC), and decreased the expression of lipid metabolism related genes such as HMGCR, LXRα, FXR and PPARγ." (PMID 37925493, 2023). "As LXRα and PPARγ are key lipogenic TFs involved in cholesterol metabolism and liver lipogenesis, the potential derepression of their activity induced by HMGB1 deletion could translate into liver steatosis." (PMID 35333579, 2022). "Additionally, clitorin significantly decreased protein expressions of sterol regulatory element-binding protein 1 (SREBP1), peroxisome proliferator-activated receptor γ (PPARγ), and CCAAT/enhancer binding protein α (C/EBPα) in WD-induced hepatic steatosis mice." (PMID 35264693, 2022). "Furthermore, it has been previously demonstrated that PPARγ could activate PI3K/AKT pathway, which then regulated the novel and direct targets HK2 and PKM2, leading to hepatic steatosis and cell proliferation." (PMID 32612951, 2020). "Thus, hepatic PPARγ activation is not indispensable for whole-body insulin-sensitizing action but contributes to the side effects of fatty liver in mice." (PMID 28611668, 2017). "Finally, PPARγ antagonism by using PPARγ antagonist GW9662, largely ameliorates body weight gain and hepatic steatosis in HFD-fed RORαLKO mice, indicating that dysregulated PPARγ signaling is a critical metabolic cue, leading to metabolic defects in HFD-fed RORαLKO mice." (PMID 28757615, 2017). "Although these findings and our own research in KKAy mice all implied a strong relationship between NAFLD and PPARγ, the effects of PPARγ on hepatic steatosis have not been conclusive, as the administration of PPARγ agonists in different animal models induced seemingly opposing effects." (PMID 26035752, 2015). "Although accumulation of hepatic lipids may lead to fatty liver, Cdk1Liv−/− mice do not have fatty liver disease based on PPARγ expression." (PMID 24613310, 2014). "The improvement of hepatic steatosis and presumably inflammation is likely due to activation of GLP-1R on hepatocytes, because others have shown that exenatide stimulates hepatocyte expression of PPARα and PPARγ that improve hepatic fatty acid oxidation, lipid export, and insulin sensitivity." (PMID 24188631, 2013). "In addition, mice lacking PPARα−/−, which develop liversteatosis, also expressed high hepatic PPARγ mRNA." (PMID 19390649, 2009). "Moreover, PPARγ plays important roles in glucose metabolism by regulating the expression of hexokinase 2 (HK2) and the M2 isoform of pyruvate kinase (PKM2), resulting in massive liver steatosis in phosphatase and tensin homologs deleted on chromosome 10 (PTEN)-null mice." (PMID 29954129, 2018).
Hepatic steatosis (continued). "Therefore, we suggest that PPARγ is an important regulator of ethanol-induced hepatic steatosis, and that the development of an MGAT1 inhibitor could be an effective therapy for treating alcoholic or non-alcoholic hepatic steatosis." (PMID 27404390, 2016). "Consequently, the effects of PPARγ on hepatic steatosis have not been conclusive, as the administration of PPARγ agonists in different animal models induces seemingly opposing effects, and the effects also differ between mice and humans, as well as among clinical studies." (PMID 24799887, 2014). "In contrast, eight weeks of arsenic exposure did not induce liver steatosis, and although it decreased CAPN1 protein levels, this exposure did not affect its proteolytic activity and PPARγ levels." (PMID 41468440, 2025). "In contrast to what has been reported in human and mouse studies, the highly significant upregulation of PPARG, CD36, LPL, and FABP4 in the liver of the minipigs do not result in development of abundant hepatic steatosis." (PMID 32205840, 2020). "While no change was seen in PPARγ protein levels in the patient serum or in the in vivo and in vitro models, the RNA sequence analysis of OA-treated cells suggested that the PPAR signaling pathway was involved in the hepatic steatosis process." (PMID 33879188, 2021).
breast cancer (390 papers, 2000 to 2026). A primary or metastatic malignant neoplasm involving the breast. "This unique environmental association between lipid metabolism and breast cancer makes it particularly interesting to study Peroxisome proliferator‐activated receptor gamma (PPARγ) gene's prominence and potential promise as a biomarker in breast cancer." (PMID 41236441, 2025). "We therefore propose that activation of the fatty acid metabolism pathway is the underlying mechanism by which PPARG initiates resistance in HER2-positive breast cancer." (PMID 40303293, 2025). "In contrast, in breast cancer and neuroblastoma, the antitumor effects of I2 have been associated with PPARG activation and a lipogenic phenotype, supporting the idea that I2 mechanisms are cell-type specific." (PMID 40869121, 2025). "While PPARγ has been implicated in lipid metabolism and adipocyte regulation, its role as a prognostic biomarker across breast cancer subtypes—particularly in relation to menopausal status and adipose metabolic activity—remains insufficiently understood." (PMID 41236441, 2025). "The nuclear receptor superfamily member, peroxisome proliferator-activated receptor gamma (PPARγ), is also a promising prognostic marker associated with longer survival in breast cancer patients." (PMID 39333940, 2024). "Dysregulation of PPARγ target gene profiles is closely linked to tumorigenesis, as underscored by the loss of CD36 resulting from repression of the PPARγ transcriptional program in breast cancer progression." (PMID 38397426, 2024). "In subtype-stratified analyses, genetically proxied PPARG perturbation was weakly associated with lower risk of ER+ breast cancer (OR 0.57 [95% CI 0.38, 0.85], p=6.45×10−3)." (PMID 37171501, 2023). "In this MR analysis of up to 287,829 cases and 606,790 controls, we found weak evidence for an association of genetically proxied PPARG perturbation with a higher risk of prostate cancer and lower risk of ER+ breast cancer." (PMID 37171501, 2023). "Collectively, these in vitro results suggested that exposure to tumor cell-secreted factors contributed to the loss of PPARγ and its target genes observed in human breast cancer specimens." (PMID 37816052, 2023). "PPARG mutations are closely associated with digestive tract cancers (colon, stomach, esophagus, and pancreas), melanoma, breast cancer, prostate cancer, and bladder cancer." (PMID 37033970, 2023). "In histological subtype-stratified analyses, genetically proxied PPARG perturbation was weakly associated with lower risk of oestrogen receptor-positive breast cancer (OR 0.57 [95% CI 0.38, 0.85], p=6.45×10−3)." (PMID 37171501, 2023). "In MR analysis we found weak evidence that genetically proxied PPARG perturbation was associated with a higher risk of prostate cancer and a lower risk of ER+ breast cancer." (PMID 37171501, 2023). "Kaplan-Meier mapper prediction studies also confirmed that low expression of PPARG was associated with worse OS in breast cancer patients." (PMID 36425653, 2022). "It is associated with longer breast cancer-specific survival and expresses more in luminal ER-positive tumors, suggesting that PPARγ is a better marker for prognosis in luminal breast cancer patients." (PMID 35190574, 2022). "The complex interactions between stroma and cancer cells are underlined by the observation that PPARγ activation in cancer cells reduces tumor growth, while overexpression in stromal cells enhances breast cancer growth in mice." (PMID 35954274, 2022). "In another study, we were able to show that RXRα and PPARγ are overexpressed in BRCA1 mutated breast cancer cases and predict prognosis." (PMID 35406808, 2022). "Taken together, the afore set of observations causally establish that PPARγ is under the negative regulation of HDACs in breast cancer." (PMID 34580286, 2021).
breast cancer (continued). "Intronic variants in PPARG (peroxisome proliferator activated receptor gamma) were associated with DA, PD, and breast cancer risk in the same direction, and with NDA and breast cancer risk in the opposite direction, as expected." (PMID 33037222, 2020). "PPARγ deficient breast cancers were insensitive to chemotherapy, but normalization of the abundant tumor vasculature with the anti-angiogenic drug sunitinib increased efficiency of cytostatic chemotherapy." (PMID 32785018, 2020). "In this latter context, PPARγ is expressed in many tumors including breast cancer, and its function upon binding of ligands has been linked to the tumor development, progression, and metastasis." (PMID 32937951, 2020). "The role of PPARγ expression in affecting breast cancer risk remains conflicting, but most studies suggest that low levels are associated with increased breast cancer risk." (PMID 32731460, 2020). "We have identified the genes which are involved in PPARγ pathway, which are which are actively involved inadipocytic differentiation andthe evidence of associativity of these genes with breast cancer has also been reported in earlier studies." (PMID 31902979, 2019). "In conclusion, this is the first study to describe VDR, RXR and PPARγ in BRCA1 mutated breast cancer." (PMID 28427429, 2017). "In the Danish prospective cohort study, variant allele carriers of peroxisome proliferator-activated receptor gamma (PPARG2) Pro12Ala (rs1801282) polymorphism had a 20% increased risk of breast cancer per 10 g of alcohol consumed per day." (PMID 28805741, 2017). "PPARγ activation induced cells to a more differentiated and caused extensive lipid accumulation in cultured breast cancer cells." (PMID 28637007, 2017). "With respect to the mouse mammary tumour outcomes observed in these studies, both MG-specific PPARγ deficiency and activation produced similar results." (PMID 25889730, 2015). "PPARγ activation induces cells to a more differentiated, less malignant state and causes extensive lipid accumulation in cultured breast cancer cells." (PMID 25119466, 2014). "Taken together, multiple lines of evidence indicate that activation/inhibition of PPARγ by natural or synthetic ligands exerts tumor modulating effects 32 and could therefore also be used to treat or prevent breast cancer surgery associated seroma development." (PMID 40940394, 2025). "PPARγ agonists hold significant promise as novel therapeutic agents for cancers, particularly those associated with chronic inflammation and immune dysfunction, such as colorectal cancer and breast cancer." (PMID 40926269, 2025). "Additionally, follow-up investigations have linked PPARγ nuclear condensates to a better prognosis in breast cancer patients, whereas patients with cytoplasmic condensates exhibit a poorer prognosis." (PMID 38383403, 2024). "PPARG is associated with breast cancer and serves as a prognostic factor for this disease." (PMID 38088228, 2024). "Given that we observed a loss of PPARγ in stromal cell types during breast cancer progression, we hypothesized that the timing of intervention was critical to the efficacy of PPARγ-directed therapy." (PMID 37816052, 2023). "Likewise, miR-155 derived from breast cancer cell exosomes promotes browning and metabolic remodeling of adipocytes through the downregulation of PPARγ, which triggers cancer-associated cachexia and facilitates tumor progression." (PMID 36670988, 2023). "Seventh, though associations of genetically proxied PPARG perturbation and prostate and ER+ breast cancer risk attenuated towards the null in iterative leave-one-out analysis removing rs4135247 from the PPARG instrument, 95% CIs overlapped across models with and without this variant." (PMID 37171501, 2023). "The risk score of breast cancer prognosis was determined with the following formula: RiskScore = 0.629*ANO6 + 0.147*CELSR3 + 0.381*CLDN7+ 0.273*EPB41L4B-0.357*FAM166B -0.843*GPLD1–0.202*LEF1–0.202*PPARG -0.127*SUSD3." (PMID 34364397, 2021).